MIR105-1 (microRNA 105-1)
Synonyms: hsa-mir-105-1; MIRN105-1; mir-105-1
Gene: MicroRNA gene on chromosome X (152,392,219 to 152,392,299, reverse strand). Ensembl gene ENSG00000207957.
Gene Ontology:
Biological process: miRNA-mediated post-transcriptional gene silencing
Cellular component: RISC complex
Homologues: Orthologues: macaque mml-mir-105-1 (100% identical), dog MIR105A (99% identical), pig ssc-mir-105-1 (99% identical), mouse Mir105 (80% identical). Paralogues in human: MIR105-2 (98% identical).